IGHMBP2 (immunoglobulin mu DNA binding protein 2)
Description:
5' to 3' helicase that unwinds both RNA and DNA duplexes in an ATP-dependent reaction (Probable). Specific to 5'-phosphorylated single-stranded guanine-rich sequences. May play a role in RNA metabolism, ribosome biogenesis or initiation of translation. May play a role in regulation of transcription (By similarity). Interacts with tRNA-Tyr. Has low processivity.
Synonyms: SMUBP2; ZFAND7; CATF1; SMARD1; HCSA; HMN6; CMT2S; HMNR1
Tractability: Small molecule: a structure with a bound ligand is known. PROTAC: ubiquitination databases record sites on it; its protein half-life has been measured.
Gene: Protein-coding gene on chromosome 11 (68,903,863 to 68,940,602, forward strand). Ensembl gene ENSG00000132740.
Subcellular location: Nucleus; Cytoplasm; Cell projection, axon
Subcellular location (Human Protein Atlas): Nucleoplasm; Cytosol; Nuclear bodies
Gene Ontology:
Molecular function: 5'-3' DNA helicase activity; 5'-3' RNA helicase activity; ATP binding; ATP hydrolysis activity; ATP-dependent activity, acting on DNA; ATP-dependent activity, acting on RNA; DNA binding; double-stranded DNA helicase activity; general transcription initiation factor binding; identical protein binding; protein binding; ribosome binding; RNA binding; single-stranded DNA binding; single-stranded RNA binding; tRNA binding; DNA helicase activity; helicase activity; nucleic acid binding; zinc ion binding
Biological process: DNA damage response
Cellular component: cytoplasm; cytosol; membrane; nuclear body; nucleoplasm; nucleus; axon; growth cone; ribonucleoprotein complex
Genetic constraint (gnomAD): Loss-of-function variants: 78 observed, 92.45 expected, observed/expected ratio (o/e) 0.84, 90% interval 0.7 to 1.02. The upper end of that interval is the gene's LOEUF score, 1.02, which puts it in group 4 of 6, group 1 being the genes least tolerant of losing a copy. Missense variants: 1,221 observed, 1,342.4 expected, observed/expected ratio (o/e) 0.91, 90% interval 0.87 to 0.95. Synonymous variants: 557 observed, 569.64 expected, observed/expected ratio (o/e) 0.98, 90% interval 0.91 to 1.05.
Gene-disease validity (ClinGen):
ClinGen rates the evidence that IGHMBP2 causes each of these diseases.
hereditary peripheral neuropathy (autosomal recessive): Definitive. An instance of peripheral neuropathy that is caused by an inherited genomic modification in an individual.
Homologues: Orthologues: chimpanzee IGHMBP2 (98% identical), macaque IGHMBP2 (95% identical), dog IGHMBP2 (82% identical), guinea pig IGHMBP2 (82% identical), rat Ighmbp2 (78% identical), mouse Ighmbp2 (78% identical), pig IGHMBP2 (76% identical), tropical clawed frog ighmbp2 (62% identical), zebrafish ighmbp2 (57% identical), Caenorhabditis elegans C05C10.2 (19% identical), Caenorhabditis elegans R03D7.2 (11% identical). Paralogues in human: SETX (20% identical), ZNFX1 (20% identical), HELZ (19% identical), HELZ2 (18% identical), UPF1 (17% identical), DNA2 (16% identical), MOV10L1 (15% identical), MOV10 (14% identical), AQR (13% identical), CT55 (1% identical).
Diseases named in the same sentence as IGHMBP2 in open-access papers:
IGHMBP2 is named in the same sentence as 52 diseases in open-access papers, as found by Europe PMC text mining. Sharing a sentence is not in itself a finding about the gene and the disease. The quoted sentences say what the papers report.
Spinal muscular atrophy with respiratory distress type 1 (12 papers, 2018 to 2026). "Pathogenic variants in the IGHMBP2 gene are associated with two distinct autosomal recessive neuromuscular disorders: spinal muscular atrophy with respiratory distress type 1 (SMARD1; OMIM #604320) and Charcot–Marie–Tooth type 2S (CMT2S; OMIM #616155)." (PMID 38415210, 2024). "Spinal muscular atrophy with respiratory distress type 1 (SMARD1) is a fatal childhood motoneuron disease caused by mutations in the IGHMBP2 gene." (PMID 38672198, 2024). "Spinal muscular atrophy with respiratory distress type 1 (SMARD1) is an autosomal recessive motor neuron disease caused by mutations in the IGHMBP2 gene (11q13)." (PMID 35976325, 2022). "Biallelic mutations in the IGHMBP2 have been associated with two distinct phenotypes: spinal muscular atrophy with respiratory distress type 1 (SMARD1) and CMT2S." (PMID 30385095, 2018). "Mutations in the Immunoglobulin Mu DNA Binding Protein 2 (IGHMBP2) gene cause Spinal Muscular Atrophy with Respiratory Distress type 1 (SMARD1), a rare, infantile, and fatal motor neuron disease, as well as the milder Charcot-Marie-Tooth disease type 2S (CMT2S)." (PMID 41486111, 2026). "IGHMBP2 loss-of-function mutations cause the rare autosomal recessive diseases spinal muscular atrophy with respiratory distress type 1 (SMARD1) and Charcot-Marie-Tooth disease type 2S (CMT2S), which are characterized by severe neurodegeneration and myopathies." (PMID 38803225, 2024). "For example, similar therapeutic strategies are proposed to applied to spinal muscular atrophy with respiratory distress type 1 (SMARD1) caused by IGHMBP2 gene mutation is a non-5q SMA, which is the second most common motor neuron disease of infancy following SMA." (PMID 32392694, 2020). "Spinal muscular atrophy with respiratory distress type 1 (SMARD1) is a rare autosomal recessive neuromuscular disorder caused by mutations in the IGHMBP2 gene, which encodes immunoglobulin μ‐binding protein 2, leading to progressive spinal motor neuron degeneration." (PMID 31802621, 2020). "Spinal muscular atrophy with respiratory distress type 1 (SMARD1, OMIM #604320) is a rare autosomal recessive hereditary degenerative motor neuron disease caused by mutations in IGHMBP2." (PMID 40686563, 2025). "An extremely rare form of SMA is Spinal Muscular Atrophy with Respiratory Distress type 1 or distal Spinal Muscular Atrophy type 1 (SMARD1/DSMA1), which is caused by a mutation in the IGHMBP2 gene, located on chromosome 11." (PMID 37372153, 2023).
spinal muscular atrophy (11 papers, 2012 to 2025). A motor neuron disease that affect the muscles, and characterized by muscle weakness and atrophy resulting from progressive degeneration and irreversible loss of the anterior horn cells in the spinal cord (i.e., lower motor neurons) and the brain stem nuclei. "In conclusion, we have established an in vitro model of induced neurons (iNs) for the study of multiple neuromuscular disorders, mainly Spinal Muscular Atrophy and IGHMBP2-related disorders." (PMID 37372153, 2023). "This study utilizes the direct conversion of skin-derived fibroblasts into iNs from patients with Spinal Muscular Atrophy (SMA) and IGHMBP2-related disorders (SMARD1/CMT2S)." (PMID 37372153, 2023). "On the other hand, mutations in IGHMBP2 lead to a large disease spectrum with no clear genotype–phenotype correlation, which includes Spinal Muscular Atrophy with Muscular Distress type 1 (SMARD1), an extremely rare form of SMA, and Charcot–Marie–Tooth 2S (CMT2S)." (PMID 37372153, 2023).
Charcot-Marie-Tooth type 2S (7 papers, 2015 to 2026). "SMA with respiratory distress type 1 (SMARD1) and Charcot-Marie-Tooth type 2S (CMT2S) are results of mutations in immunoglobulin mu DNA binding protein 2 (IGHMBP2)." (PMID 36480289, 2023). "Moreover, it is well recognized that IGHMBP2 variants can also result in the milder axonal neuropathy Charcot-Marie-Tooth disease type 2S (CMT2S)." (PMID 41486111, 2026). "Mutations within the immunoglobulin mu DNA binding protein (IGHMBP2), an RNA–DNA helicase, lead to SMA with respiratory distress type I (SMARD1) and Charcot-Marie-Tooth type 2S (CMT2S)." (PMID 39815358, 2025). "Homozygous or compound heterozygous mutations in immunoglobulin mu DNA binding protein 2 (IGHMBP2) result in 2 distinct diseases: SMA with respiratory distress type 1 (SMARD1) and Charcot-Marie-Tooth type 2S (CMT2S)." (PMID 36480289, 2023). "It should be noted that mutations in the IGHMBP2 gene do not always result in SMARD1 but may also lead to a milder form of neurodegeneration, namely Charcot-Marie-Tooth type 2S (CMT2S) disease." (PMID 36077311, 2022).
motor neuron disease (5 papers, 2014 to 2026). "However, SMARD1 — just like SMA and ALS — is not exclusively a motor neuron disease; therefore, IGHMBP2 deficits in other tissues not reached by scAAV9-Abt1 delivery remain impacted." (PMID 36480289, 2023).
neuropathies (4 papers, 2023 to 2025). "CMT2S, caused by biallelic IGHMBP2 variants, usually presents as a severe, progressive neuropathy in the first decade." (PMID 40869966, 2025). "Our work demonstrates the utility of studying neuropathy-associated gene IGHMBP2 in an immature human cell line, expands on the fundamental relevance of IGHMBP2, and reinforces the significance of translation in cellular health." (PMID 38803225, 2024). "With recent studies showing the integrated stress response (ISR) can contribute to tRNA metabolism-linked neuropathies, we asked whether perturbing IGHMBP2 promotes ISR activation." (PMID 38803225, 2024). "With recent studies showing the ISR can contribute to tRNA metabolism-linked neuropathies, we asked whether perturbing IGHMBP2 promotes ISR activation." (PMID 38168189, 2023). "In parallel, another early-stage clinical trial is underway to deliver a functional IGHMBP2 gene for treating IGHMBP2-related neuropathies, including CMT2S (NCT05152823)." (PMID 40831607, 2025). "This trial, sponsored by the NIH and investigating AAV9-mediated gene delivery for IGHMBP2-related neuropathies, could offer therapeutic benefit in selected cases." (PMID 40869966, 2025).
respiratory failure (4 papers, 2024 to 2025). The significant impairment of gas exchange within the lungs resulting in hypoxia, hypercarbia, or both, to the extent that organ tissue perfusion is severely compromised. "The presence of respiratory failure of varying severity suggests a continuous spectrum of IGHMBP2-related disorders." (PMID 39457418, 2024).
adrenomyeloneuropathy (2 papers, 2024). An adult form of the peroxisomal disease X-linked adrenoleukodystrophy (X-ALD), characterized by spastic paraparesia and often associated with peripheral adrenal insufficiency in males. "Among the genetic diseases mentioned are Adrenomyeloneuropathy (AMN), Canavan Disease (CD), Giant Axonal Neuropathy (GAN), IGHMBP2 Related Diseases (IGHMBP2), Late Infantile Neuronal Ceroid Lipofuscinosis (LINCL), Menkes Syndrome (MS), and Spastic Paraplegia type 50 (SP50)." (PMID 39062095, 2024). "Among the genetic diseases mentioned are Adrenomyeloneuropathy (AMN), CD, SMA (15% of trials), HD, Giant Axonal Neuropathy, IGHMBP2-Related Diseases, Late Infantile Neuronal Ceroid Lipofuscinosis, Menkes Syndrome and spastic paraplegia type 50." (PMID 39682723, 2024).
and sensory neuropathy (2 papers, 2016 to 2018). "We describe a patient with childhood onset autosomal recessive motor and sensory neuropathy with severe organ-specific autonomic dysfunction due to a novel IGHMBP2 missense variant." (PMID 30385095, 2018).
Charcot-Marie-Tooth disease (2 papers, 2022 to 2024). An inherited degenerative disorder involving the peripheral nerves. "A pair of variants in IGHMBP2 (HGNC:5542), a gene known to cause Charcot-Marie-Tooth disease (CMT), were found in a proband reported to have CMT disease." (PMID 39243181, 2024).
dilated cardiomyopathy (2 papers, 2013 to 2026). Cardiomyopathy which is characterized by dilation and contractile dysfunction of the left and right ventricles. "It is well known that the nmd mouse model develops dilated cardiomyopathy, even when IGHMBP2 expression is selectively rescued in neurons only." (PMID 41486111, 2026).
spinal muscular atrophy, type 1 (2 papers, 2015 to 2024). A severe infantile form of proximal spinal muscular atrophy characterized by severe and progressive muscle weakness and hypotonia resulting from the degeneration and loss of the lower motor neurons in the spinal cord and the brain stem nuclei. "Homozygous mutations in IGHMBP2 are known to cause spinal muscular atrophy type 1, which has clinical features matching those of S9." (PMID 25356967, 2015).
autonomic dysfunction (1 paper, 2018). "This case report confirms that IGHMBP2 related disorders can result in a severe peripheral neuropathy with gastrointestinal autonomic dysfunction requiring parenteral nutrition." (PMID 30385095, 2018). "Sensory involvement and autonomic dysfunction, including excessive sweating, tachycardia, constipation and bladder dysfunction, have been described in patients with SMARD1 but also in patients with CMT2S due to IGHMBP2 mutations." (PMID 30385095, 2018).
autonomic neuropathy (1 paper, 2018). An inherited or acquired peripheral neuropathy affecting the autonomic nervous system. "We suggest that mutations in IGHMBP2 may cause an early onset severe sensory motor axonal neuropathy in association with severe organ specific autonomic neuropathy affecting the gastrointestinal tract." (PMID 30385095, 2018).
distal arthrogryposis (1 paper, 2018). A muscle tissue disease characterized by congenital joint contractures of hand and feet. "Expression of several genes linked to motor neuronopathy and familiar amyotrophic lateral sclerosis (EPHA4, IGHMBP2, VAPB, BICD2, and DYNC1H1) or distal arthrogryposis (MYH8, ZC4H2, MUSK, RAPSN) were significantly upregulated or downregulated." (PMID 29727687, 2018).
Sensorimotor neuropathy (1 paper, 2025). "Symptoms emerged when the patient began walking and evolved into progressive sensorimotor neuropathy without respiratory distress, thereby expanding the phenotypic spectrum of IGHMBP2-related disease." (PMID 40869966, 2025).
neuromuscular disease (5 papers, 2015 to 2025). "Spinal muscular atrophy with respiratory distress (SMARD1) is an autosomal recessive neuromuscular disease caused by mutations in the IGHMBP2 gene, encoding the immunoglobulin μ-binding protein 2, leading to motor neuron degeneration." (PMID 26095024, 2015). "IGHMBP2 is a non-essential, superfamily 1 DNA/RNA helicase that is mutated in patients with rare neuromuscular diseases SMARD1 and CMT2S." (PMID 38168189, 2023).
neurodegenerative disease (3 papers, 2020 to 2026). A disorder of the central nervous system characterized by gradual and progressive loss of neural tissue and neurologic function. "Given the role of ATF4 as part of the ISR and the relevance of the ISR in neurodegenerative diseases, we wondered if ISR activation is a consequence of IGHMBP2 deletion." (PMID 38803225, 2024).
peripheral neuropathy (3 papers, 2018 to 2024). A disorder affecting the peripheral nervous system. "Mutations in the IGHMBP2 gene have also been found in patients with peripheral neuropathy Charcot–Marie–Tooth type 2S (CMT2S)." (PMID 38672198, 2024). "IGHMBP2 mutations in patients do not only exclusively lead to motoneuron loss; they also lead to peripheral neuropathies for reasons that are still unknown." (PMID 38672198, 2024). "•Novel IGHMBP2 variant found in a patient with early onset severe peripheral neuropathy." (PMID 30385095, 2018). "Rare variants (RV) in immunoglobulin mu‐binding protein 2 (IGHMBP2) [OMIM 600502] can cause an autosomal recessive type of Charcot‐Marie‐Tooth (CMT) disease [OMIM 616155], an inherited peripheral neuropathy." (PMID 31020813, 2019).
tumor (2 papers, 2023 to 2025). "A differential abundance analysis between proteomes of NK cells isolated from liver and tumor tissues identified four proteins that were increased in tumor NK cells (Log2 fold change > 2; p value < 0.01): AKR1B10, GLUL, IGHMBP2, and AFAP1L2." (PMID 37388918, 2023).
genetic disorder (1 paper, 2026). "The present study marks a pivotal advance in gene therapy targeting SMARD1, a rare fatal genetic disorder caused by mutations in IGHMBP2 gene, lacking approved efficacious treatments." (PMID 41486111, 2026).
IGHMBP2 also shares sentences with these, for which no sentence is quoted: distal hereditary motor neuronopathy (2 papers); distal hereditary motor neuropathy type 6 (2); Parkinson disease (2); Skeletal myopathy (2); adrenoleukodystrophy (1); Alzheimer disease (1); amyotrophic lateral sclerosis (1); Atrophy (1); autosomal recessive disease (1); breast carcinoma (1); cancer (1); cataract (1); congenital myopathies (1); distal muscular atrophy (1); frontotemporal dementia (1); Genetic motor neuron disease (1); hereditary spastic paraplegia (1); Huntington disease (1); IgA nephropathy (1); late infantile neuronal ceroid lipofuscinosis (1); motor neuron degeneration (1); muscular dystrophies (1); myopathy (1); myotonic dystrophy (1); neurological diseases (1); pontocerebellar hypoplasia, type 1C (1); Primary lateral sclerosis (1); prostate carcinoma (1); Respiratory insufficiency (1); sarcoma (1).
A further 2 diseases each share a sentence with IGHMBP2 in 1 paper.